DCX (doublecortin)
Diseases named in the same sentence as DCX in open-access papers (continued):
Sharing a sentence is not in itself a finding about the gene and the disease.
breast cancer (8 papers, 2017 to 2026). A primary or metastatic malignant neoplasm involving the breast. "Stromal presence of DCX + cells is associated with tumours of higher histological grade, a basal-like phenotype, and shorter patient survival in tumour tissue from patients with breast cancer." (PMID 39232464, 2024). "Overall, our data indicate that stromal presence of DCX + cells in breast cancers (n = 107) associates with aggressive tumour features, suggesting that these cells may play a role in breast cancer progression." (PMID 39232464, 2024). "Functions: Shows stromal DCX+ neural progenitor cells are associated with aggressive breast cancer and poor survival; proteomics reveals co-evolution changes.Unsolved: The specific functional mechanisms through which neural progenitors influence breast cancer progression remain to be elucidated." (PMID 41601691, 2026). "The proportion of stromal DCX + cells were higher among basal-like breast cancers and in tumours with higher histological grade." (PMID 39232464, 2024). "Here, we investigate the presence of DCX-expressing cells in breast cancer stromal tissue from patients using Imaging Mass Cytometry." (PMID 39232464, 2024). "When comparing the proportion of stromal DCX + cells in basal-like vs. luminal-like breast cancer tissue, we found higher proportion of DCX + cells in basal-like breast tumours." (PMID 39232464, 2024). "Here, we aim to explore the presence and localization of DCX + cells in primary breast cancer tissue by single-cell spatial proteomics using Imaging Mass Cytometry (IMC)." (PMID 39232464, 2024). "Still, our findings appear to suggest a preference for NPC integration in basal-like spheroids, which agree with higher stromal presence of DCX + cells in basal-like breast cancer by IMC analysis, although further studies would be needed to confirm this observation." (PMID 39232464, 2024). "In our present study, we explored whether a similar mechanism might occur in breast cancer by investigating presence and localization of DCX + cells in luminal-like and basal-like tumours." (PMID 39232464, 2024). "As such, our in vitro models and breast cancer tissue spatial proteomics analysis do not demonstrate any causal effect of reduction of DCX + stromal cells in breast cancer and needs to be validated by in vivo model experiments." (PMID 39232464, 2024). "Whether breast cancer contain stromal DCX + cells that might contribute to tumour neurogenesis, and how direct-contact co-culture interaction with NPCs would influence breast cancer cells at the functional protein level, remains unknown." (PMID 39232464, 2024). "Our data indicates that stromal presence of DCX + cells may play a role in breast cancer progression which warrants further investigations into the direct relationship between neural progenitors and breast cancer cells." (PMID 39232464, 2024). "In three breast cancer cohorts, we evaluated the link between hormonotherapy response and gene expression of the two previously used brain NPC markers (DCX and PTPRZ1)." (PMID 36923306, 2022). "DCX + cells in patient breast cancer tissue did not express TH, nor did we find TH expression in our GFP + cells in the in vitro co-culture model following proteomics analysis." (PMID 39232464, 2024). "Neural stem and progenitor markers such as MSI1, DCX, NFL, HMGB1 were all significantly decreased after co-culture with breast cancer cells, suggesting that interaction with breast cancer cells leads to initiation of neural differentiation and maturation of NPCs." (PMID 39232464, 2024).
prostate tumors (8 papers, 2020 to 2025). "In this study, based on the Hi‐Myc prostate adenocarcinoma mouse model, the genetic depletion of DCX+ cells, as well as the surgical or chemical ablation of sympathetic nerves, inhibited prostate tumor growth and metastases." (PMID 40591148, 2025). "Neural progenitors from the brain that express doublecortin (DCX+) can migrate to prostate tumors and initiate neurogenesis, leading to tumor growth and metastasis." (PMID 36499024, 2022). "Additionally, it has been reported that doublecortin (DCX+) neural progenitors from the central nervous system (CNS) can infiltrate prostate tumors and differentiate into new adrenergic sympathetic neurons." (PMID 40591148, 2025). "We found positive stromal staining for DCX, similar to findings in prostate tumours." (PMID 39232464, 2024). "Furthermore, neural progenitor cells expressing the neural stem cell marker doublecortin (DCX+) initiate neurogenesis in prostate tumors." (PMID 36105204, 2022).
microcephaly (7 papers, 2014 to 2026). A congenital or acquired developmental disorder in which the circumference of the head is smaller than normal for the person's age and sex. "Similarly, our data also demonstrated a decrease of DCX levels in ZIKV-infected fetal brain concomitant with an obvious defect in cortical structure formation, implying a potential mechanism for ZIKV-induced microcephaly via regulation of the neural migration process." (PMID 29922247, 2018).
glioblastoma (6 papers, 2016 to 2021). The most malignant astrocytic tumor (WHO grade IV). "Hypoxia tolerance is also found in glioblastoma cell line U-87 after induction to express the neural progenitor protein doublecortin (DCX)." (PMID 26915110, 2016). "Subsequent culture of C6 cells as neurospheres (glioblastoma stem-like cells, GBSC) suspended in DME/F12 medium supplemented with EGF, bFGF, and B27 supplement also indicated DCX expression." (PMID 32050972, 2020). "Identification of DCX expression in oligodendroglial precursor cells (OPC) was proposed to reflect cell migration rather than neuronal differentiation and DCX expression is also speculated to have a role in glioblastoma infiltration." (PMID 30005693, 2018).
neuronal migration disorders (6 papers, 2009 to 2024). "Doublecortin (Dcx) is a microtubule binding protein that when mutated causes a type of neuronal migration disorder known as X-linked lissencephaly." (PMID 19320973, 2009). "Indeed, several studies revealed that the mutations in the genes encoding LIS1 and DCX in humans cause distinct neuronal migration disorders." (PMID 24489718, 2014). "Downregulation of DCX by RNA interference in animal models leads to neuronal migration disorders similar to those seen in the brains of dyslexic individuals." (PMID 26331477, 2015).
Pachygyria (6 papers, 2016 to 2024). Pachygyria is a malformation of cortical development with abnormally wide gyri with sulci 1,5-3 cm apart and abnormally thick cortex measuring more than 5 mm (radiological definition). "Doublecortin is involved in neuronal migration and DCX loss‐of‐function mutations are responsible for X‐linked lissencephaly in hemizygous males (MIM# 300067) with symptoms that include pachygyria, seizures, and delayed motor development." (PMID 30632316, 2019).
ZIKV infection (6 papers, 2016 to 2023). "Other than that, Doublecortin (DCX), a microtubule-associated protein that plays an essential role in neurogenesis was downregulated at both mRNA and protein levels during ZIKV infection in NPCs and fetal mouse brains." (PMID 35371036, 2022). "Results showed that ZIKV infection downregulated DCX, at both mRNA and protein levels, as early as 1 day post infection (1 dpi), and lasted throughout the virus replication cycle (4 days)." (PMID 29922247, 2018). "The downregulation of both DCX mRNA and protein levels by ZIKV infection implies the existence of distinct mechanisms in ZIKV that impact transcriptional and protein levels in the host." (PMID 29922247, 2018). "How these observed changes of DCX expression translate in the pathological consequences of ZIKV infection and if other cellular proteins are equally involved remains to be investigated." (PMID 29922247, 2018). "Our data further verified that one of the key factors in neural migration, DCX, was downregulated during ZIKV infection in infected NPCs and fetal mouse brains." (PMID 29922247, 2018). "Other models of ZIKV infection have found a decrease in DCX at the mRNA and protein levels." (PMID 37631975, 2023). "Proteins previously identified to be differentially expressed during ZIKV infection include GAP43, DCX, PTPRZ1, ASNS, SLC3A2 and MKI67." (PMID 32873194, 2020). "Proteomic analysis showed that DCX, one of the important NPC markers, was downregulated by ZIKV infection at 1 dpi (0.77-fold comparing to mock)." (PMID 29922247, 2018). "The relative DCX protein levels decreased ~25% in ZIKV-infected fetal brains compared to the mock-infected ones, suggesting that ZIKV infection can decrease DCX protein level in fetal brain." (PMID 29922247, 2018). "Many of these proteins have been shown to be related to cellular functions of neural cells, and are found to play roles in cell signaling processes, such as DCX, EGFR, and GAP43, indicating the alteration of multiple cell signaling pathways in NPC by ZIKV infection." (PMID 29922247, 2018). "However, the impact of ZIKV infection on the expression of DCX in NPCs has not been investigated." (PMID 29922247, 2018).
autism (5 papers, 2015 to 2024). Persistent deficits in social interaction and communication and interaction as well as a markedly restricted repertoire of activity and interest as well as repetitive patterns of behavior. "Expression analysis for DCX transcript, a marker of neuronal migration, revealed 80% reduced expression in autism, while MKI67 expression level was the same in both groups." (PMID 38994948, 2024). "Moreover, the candidate genes PAK3, OCRL, DCX, PTK2, KCNQ3, SOX3, and LAMA1 were associated with autism, brain disease, Dent disease, and other conditions that present ID as a hallmark, corroborating our findings." (PMID 33922640, 2021). "Post hoc analyses showed a statistically significant decrease, such that there was a >40% reduction in the mean densities of immature DCX+ neurons in the ventral dentate gyrus in both mouse models of autism compared to wild-type mice (WT vs Cntnap2−/−, p = 0.02; WT vs Shank3+/ΔC, p = 0.02)." (PMID 27785461, 2016).
diabetes (5 papers, 2010 to 2024). "The findings indicated that the hippocampal protein expression of DCX in the diabetes mice was markedly lower than those in the control group." (PMID 39452118, 2024). "Genetic and pharmacological rodent models of diabetes also demonstrate impaired neurogenesis, including reductions in Ki67 and DCX in the dentate." (PMID 31871124, 2020). "This expands the functional scope of DCX and calls for further research into the relationship between neurogenesis and the production of new beta cells in response to diabetes." (PMID 28701917, 2017). "This further exposes the versatility of the DCX protein in cellular activities and can open a broad spectrum as to the relationship between neurogenesis and the production of new beta cells in response to diabetes." (PMID 28701917, 2017). "Interestingly, cells expressing DCX, that will generate mature granule neurons, were described as specially responsive to certain enrichment paradigms and, in contrast, particularly vulnerable in conditions such as diabetes, aging and chronic stress." (PMID 21085588, 2010).
memory impairment (5 papers, 2018 to 2024). "This is similar to the results of our previous research, which found that memory impairment caused by VPA in an animal model is related to decreases in the population of DCX-positive cells in the hippocampal DG." (PMID 34804374, 2021). "Doublecortin elevation has also been implicated in brain inflammation and the resultant short‐term memory impairment in rats, while miR‐203 has been implicated in the alleviation of inflammation, oxidative stress and apoptosis in rats with lung injuries." (PMID 32783282, 2020). "Considering that hippocampal neurogenesis dysfunction is correlated with learning and memory impairment, we assessed the number of DCX-positive immature neurons and Ki67-positive neuronal precursors in the DG, and found they were all decreased in young CpGfapcKO mice." (PMID 36443285, 2022).
brain tumor (4 papers, 2017 to 2024). "DCX is a microtubule-associated protein at the crossroads between brain tumors and neurodevelopmental disorders, primarily known for its role in neuronal development and migration." (PMID 39719558, 2024). "Several kinases and phosphatases involved in the phosphorylation and dephosphorylation of DCX have been implicated in brain tumor proliferation and invasion." (PMID 28701917, 2017). "DCX-stained brain tumor sections showed higher amount of cells expressing DCX in the nuclear compartment, and these cells are mainly located at the invasive edge of the protruding tumor mass, unlike the wt-C6 tumor where nuclear-DCX positive cells are closer to the center of the tumor mass." (PMID 32050972, 2020). "What effect does DCX have on the proliferation capacity of brain tumors?" (PMID 28701917, 2017).
Obesity (4 papers, 2019 to 2023). Accumulation of substantial excess body fat. "To next evaluate the effects of maternal obesity on hypothalamic neuronal network plasticity, we first determined protein expression of doublecortin (DCX), a specific marker for newborn neurons, in the hypothalamus of HFD and CO offspring at P21." (PMID 31572115, 2019). "Notably, a study involving mice with long-term obesity revealed ER stress and CHOP expression in DCX-expressing immature neurons, indicating a common mechanism of ER stress-related neurogenesis impairment." (PMID 37958604, 2023).
viral infection (4 papers, 2011 to 2023). "We next examined if viral infection is associated with abnormal expression of structural proteins such as doublecortin (DCX) and GFAP." (PMID 21249143, 2011). "In sections containing areas of rostral migratory stream, we observed viral infection in immature neurons, identified by doublecortin (DCX) immunoreactivity in both WT and Ifnar–/– brains." (PMID 37037810, 2023). "Although viral infection is not considered a quantitative measure of neurogenesis, these findings are in line with our findings from DCX staining and IdU-labeling." (PMID 30618601, 2018).
brain malformations (3 papers, 2015 to 2018). "Consistent with the important roles of the microtubule network in neuronal migration, mutations in LIS1 and the microtubule regulator doublecortin/DCX are associated with migration disorders that give rise to brain malformations." (PMID 29057214, 2017).
cognitive decline (3 papers, 2020 to 2024). "Notably, NOP exploration ratios positively correlate with percentage of GCL area covered by DCX+ neurons, suggesting that reduced integration of adult born neurons into hippocampal circuity may contribute to the cognitive decline and recovery in this model following AIE and AD transgenes." (PMID 39148897, 2024).
Down syndrome (3 papers, 2017 to 2022). "However, consistent with previous studies in rats and Ts65Dn Down’s syndrome (DS) model mice, perinatal choline supplementation significantly upregulated dentate gyrus DCX staining and hippocampal DCX levels in both WT and APP.PS1 mice." (PMID 28103298, 2017).
Hydrocephalus (3 papers, 2008 to 2023). Hydrocephalus is an active distension of the ventricular system of the brain resulting from inadequate passage of CSF from its point of production within the cerebral ventricles to its point of absorption into the systemic circulation. "When stained with a marker for radial glia and migrating neuroblast, the TMEM67 mutant with hydrocephalus displayed an increase of radial distribution of vimentin+ and DCX+ cells in the cerebral cortex as compared to the wild type animals." (PMID 27243144, 2016). "Both DCX and GPC2 associated with hydrocephalus, NSE, IL-1β, IL-2, IL-8, IL-13." (PMID 36800341, 2023). "Unlike the previous report, we have not detected hydrocephalus in our Nfix-/- mice, but instead find unusual Pax6- and DCX-positive cells within the lateral ventricles of the mice." (PMID 18477394, 2008).
hypothyroidism (3 papers, 2010 to 2024). Abnormally low levels of thyroid hormone. "Developmental iodine deficiency and hypothyroidism impair the expression of doublecortin and NCAM-180, leading to nerve fiber malfunction and thus impairments in hippocampal development." (PMID 20412599, 2010). "Developmental iodine deficiency and hypothyroidism depress the expression of doublecortin and enhance the NCAM-180, leading to nerve fiber morphology abnormalities and probable malfunction, and thus impairments in hippocampal development." (PMID 20412599, 2010). "For instance, by examining specific markers such as doublecortin (DCX), which is indicative of adult neurogenesis, researchers have gained insights into the biological defects caused by hypothyroidism, leading to structural and functional impairments in the hippocampus." (PMID 38298204, 2023). "Therefore, we chose doublecortin, a biomarker for neuronal development, to investigate how iodine deficiency and hypothyroidism affect neural differentiation." (PMID 20412599, 2010). "Adult-onset hypothyroidism led to decreased precursor cell survival and a reduced number of DCX positive progenitor cells in rodents." (PMID 38516412, 2024). "Recently, a genomic analysis of subclinical hypothyroidism detected changes of doublecortin and NCAM 1 in the neocortex of the developing rat brain." (PMID 20412599, 2010). "Here, we explored the roles of hippocampal doublecortin and neural cell adhesion molecule (NCAM)-180 in developmental iodine deficiency and hypothyroidism." (PMID 20412599, 2010). "Considering that doublecortin regulates the migration of cortical neurons via actions at the distal ends of neurites that promote neurite extension, it is conceivable that doublecortin may be involved in neural developmental deficits caused by iodine deficiency and hypothyroidism." (PMID 20412599, 2010). "Given that doublecortin is a marker of new neurons and expresses in differentiating and migrating neurons, a reduction of doublecortin by dietary iodine deficiency and PTU-induced hypothyroidism in the present study is in agreement with a reduction in nerve fibers and newborn neurons." (PMID 20412599, 2010). "A detailed mechanism is still lacking by which developmental iodine deficiency and hypothyroidism regulate doublecortin and NCAM proteins and deserves further investigation." (PMID 20412599, 2010). "However, relatively little is known about whether doublecortin and NCAM-180 expressions are affected following iodine deficiency or PTU induced-hypothyroidism." (PMID 20412599, 2010).
Allergy (2 papers, 2016 to 2018). An allergy is an immune response or reaction to substances that are usually not harmful. "Moreover, there is a related report that allergy led to a reduced microglia presence and activity and to an elevated level of neurogenesis, such as those of DCX(+) cells and BrdU(+) cells in the hippocampus of allergic mice." (PMID 29849816, 2018). "The number of DCX+ cells was clearly increased in the allergy animals." (PMID 27445696, 2016). "Indeed, allergic mice had an increased number of DCX+ cells in the GL and SGZ of the dorsal dentate gyrus (control: 2659 ± 337 cells per hemisphere, allergy: 3395 ± 591 cells per hemisphere; p < 0.0064)." (PMID 27445696, 2016).
Arthritis (2 papers, 2021). Inflammation of a joint. "On the other hand, TNF-α has a positive correlation with the number of DCX+ and Ki67+ cells in the dentate gyrus in females, which may indicate a faster recovery of adult neurogenesis but at the same time, may worsen the clinical course of arthritis." (PMID 34830044, 2021).